IGF2BP3 (insulin like growth factor 2 mRNA binding protein 3)
Diseases named in the same sentence as IGF2BP3 in open-access papers (continued):
Sharing a sentence is not in itself a finding about the gene and the disease.
melanoma (37 papers, 2013 to 2025). A malignant, usually aggressive tumor composed of atypical, neoplastic melanocytes. "IGF2BP3 promotes the proliferation and migration of melanoma cells and is associated with the infiltration level of immune cell in the TIME." (PMID 39028290, 2024). "IGF2BP3 is a potential melanoma diagnostic and prognostic biomarker, and, in our study, IGF2BP3 mRNA and its protein counterparts (H-scores 1 and 2) showed a significant and moderate positive correlation." (PMID 35565448, 2022). "Our findings highlight the feasibility of using RT-qPCR, instead of IHC, for the routine assessment of IGF2BP3 in order to assist in the selection of melanoma patients with a higher risk of developing distant metastasis or dying from melanoma." (PMID 35565448, 2022). "Insulin-like growth factor-II mRNA-binding protein 3 (IGF2BP3) has emerged as a potential melanoma diagnostic and prognostic biomarker." (PMID 35565448, 2022). "Conversely, IGF2BP3 mRNA expression showed more significant associations with more melanoma parameters and with a higher level of significance." (PMID 35565448, 2022). "Meanwhile, we explored the obtainable effects of anti-tumor drugs for melanoma patients with IGF2BP3 mutations, revealing significantly epigenetic regulators of melanoma and novel approaches in precise and personalized medicine therapy." (PMID 34446007, 2021). "In our study, IGF2BP3 in melanoma has been linked with tumourigenic properties and poor prognosis, making it a potential target for drug development." (PMID 34446007, 2021). "Coefficients obtained from multivariate Cox analysis were conducted to calculate each melanoma patient’s risk score utilizing the following formula: risk score = (0.675902669) × RBM15B + (0.6078590311) × METTL16 + (0.555973734) × IGF2BP3." (PMID 34446007, 2021). "The CellMiner screening results revealed that trametinib and cobimetinib exhibited sensitivity for melanoma patients with IGF2BP3 mutations." (PMID 34446007, 2021). "We found that IGF2BP3 mRNA expression correlated better with clinicopathologic melanoma features than the corresponding proteins and that patients with higher IGF2BP3 mRNA levels were at more risk for earlier development of metastasis, confirming its impact on melanoma survival." (PMID 35565448, 2022). "Loss of circCDR1as induces melanoma invasion and metastasis via interaction with IGF2BP3." (PMID 35039066, 2022). "Our results indicate that the IGF2BP3 mRNA median value was a valid cut-off which reliably distinguishes between patients with higher and lower risk of developing distant metastasis and dying of melanoma." (PMID 35565448, 2022). "IGF2BP3 mRNA showed a stronger association with clinicopathologic factors (Breslow thickness, ulceration, mitosis rate, growth phase, development of metastasis, and melanoma-specific survival) than its protein counterpart." (PMID 35565448, 2022). "In conclusion, high IGF2BP3 mRNA levels are associated with a more aggressive tumor behavior and worse clinical outcomes, supporting its use as an effective prognostic biomarker even in the earlier stages of melanoma development." (PMID 35565448, 2022). "In addition, IGF2BP3 was verified to promote melanoma cell proliferation and migration in vitro and associate with lymph node metastasis in clinical samples." (PMID 34446007, 2021). "These discoveries imply that risk score and IGF2BP3 might be involved in immune infiltration governing in melanoma." (PMID 34446007, 2021). "Moreover, risk score and the expression of IGF2BP3 were positively associated with the infiltrating immune cells and these hub genes made excellent potential drug targets in melanoma." (PMID 34446007, 2021). "In our study, cobimetinib and trametinib exhibited sensitivity for melanoma with IGF2BP3 mutations." (PMID 34446007, 2021).
melanoma (continued). "Therefore, RT-qPCR may successfully be implemented for routine IGF2BP3 assessing for the selection of melanoma patients with a higher risk of developing distant metastasis and dying of melanoma." (PMID 35565448, 2022). "Several m6A regulators including METTL3, YTHDF1, HNRNPA2B1, FTO, and IGF2BP3 are involved in melanoma." (PMID 37124930, 2023). "We have found that patients with high expression levels of IGF2BP1 and IGF2BP3 have statistically significant poorer survival rates compared to those whose melanoma cells had low IGF2BP1 and IGF2BP3 levels." (PMID 37503349, 2023). "Analysis of data from human melanoma patients indicates that high levels of IGF2BP1 and IGF2BP3 are associated with resistance to immunotherapies and poor survival." (PMID 37503349, 2023). "Our retrospective data analysis of immunotherapies in human melanoma patients indicates that high levels of IGF2BP1 and IGF2BP3 are associated with resistance to immunotherapies and poor prognosis." (PMID 37503349, 2023). "In melanoma, CDR1as has been reported to unleash pro-metastatic functions of IGF2BP3, which shed new light onto the proteomics of CDR1as." (PMID 37004067, 2023). "For instance, in melanoma, IGF2BP3 promotes migration and invasion through direct regulation of HMGA2 transcripts." (PMID 37760460, 2023). "On the other hand, insulin-like growth factor-II mRNA-binding protein 3 (IGF2BP3) has also been recently highlighted to be a noteworthy marker of melanoma diagnosis and prognosis." (PMID 35565448, 2022). "High IGF2BP3 expression enhanced melanoma cell proliferation by accelerating the degradation of EIF4E-BP2 mRNA and promoting the translation of EIF4E." (PMID 35676262, 2022). "Nevertheless, our study points to promising results, providing proof that IGF2BP3 would be a reliable prognostic factor even for the earliest stages of melanoma development." (PMID 35565448, 2022). "This tendency was also observed in the primary tumors of patients who died from melanoma for both IGF2BP3 mRNA and protein (H-score 1) (p = 0.009 and p = 0.029, respectively)." (PMID 35565448, 2022). "Both (DMFS and MSS) were significantly shorter in patients with primary melanomas showing IGF2BP3 mRNA expression levels above the median (median MSS: 60.81% vs. 89.88%, p = 0.015 and median DMFS: 47.79% vs. 89.33%, p < 0.001, respectively)." (PMID 35565448, 2022). "IGF2BP3 expression has also been considered for its potential use in the differential diagnosis of malignant melanoma with other benign skin lesions." (PMID 35565448, 2022). "In the Kaplan–Meier analysis, we observed a significant inverse correlation between the IGF2BP3 expression level and the melanoma-specific and distant metastasis-free survival rates." (PMID 35565448, 2022). "The Kaplan–Meier survival analysis showed that IGF2BP3 mRNA expression was significantly associated with clinical endpoints such as distant metastasis-free survival (DMFS) and melanoma-specific survival (MSS)." (PMID 35565448, 2022). "In this study, we evaluated the prognostic performance of two methods for assessing IGF2BP3 gene expression, one based on protein quantification (IHC) and the other on mRNA quantification (RT-qPCR) in the same cohort of melanoma patients." (PMID 35565448, 2022). "Our goal was to investigate the clinical significance of IGF2BP3 (mRNA and protein) in melanoma progression and evaluate which quantification method, RT-qPCR or IHC, provides a higher prognostic value of the expression of IGF2BP3 among primary melanomas." (PMID 35565448, 2022). "In this context, the present work analyzes and compares the prognostic value of IGF2BP3 mRNA versus protein expression in primary melanomas in terms of their efficiency to predict the clinical outcomes of patients." (PMID 35565448, 2022). "We also found sequential upregulation of intratumoral expression of IGF2BP3 mRNA over the full spectrum of melanoma progression." (PMID 35565448, 2022).
melanoma (continued). "CDR1as interacts with the Insulin-like growth factor-binding protein 3 (IGF2BP3); its silencing activates IGF2BP3 and promotes melanoma invasion, resistance to GPX4 inhibitors, and tumor growth in vivo." (PMID 35159386, 2022). "A progressive increase in IGF2BP3 mRNA expression was found along the full spectrum of melanoma progression, from thin primary melanomas to distant metastatic tumors (p < 0.001)." (PMID 35565448, 2022). "Particularly, we found a significant and positive correlation between IGF2BP3 mRNA expression and both Breslow thickness and mitotic index in primary melanomas." (PMID 35565448, 2022). "First, we analyzed if a correlation between the mRNA (RT-qPCR) and protein (IHC) expression values of IGF2BP3 exists in the primary melanoma tissue samples, where both the IGF2BP3 gene and protein were measured (n = 54)." (PMID 35565448, 2022). "And IGF2BP3 showed a significantly higher expression level (P < 0.05) in metastasis melanoma tissues than in the primary melanoma tissues." (PMID 34446007, 2021). "Secondly, we explored the relevance of the signature and IGF2BP3 with immune infiltration in melanoma, which highlighted the relationship between tumor epigenetic heterogeneity and immune contexture." (PMID 34446007, 2021). "CCK-8, colony formation, and EDU assays indicated that IGF2BP3 knockdown significantly inhibited melanoma cell proliferation, and IGF2BP3 overexpression promoted melanoma cell proliferation." (PMID 34446007, 2021). "A three-gene prognostic signature including IGF2BP3, RBM15B, and METTL16 was constructed, and the risk score of this signature was identified to be an independent prognostic indicator for melanoma." (PMID 34446007, 2021). "Overall, we performed a systematic evaluation of the underlying regulatory mechanisms of IGF2BP3 and its effects on prognosis, the infiltration of immune cells, the levels of CNV, and therapeutic sensitivity in melanoma." (PMID 34446007, 2021). "Correlations between the expression of IGF2BP3 and clinicopathological features in melanoma patients were calculated, IGF2BP3 level was significantly correlated with lymph node metastasis in melanoma." (PMID 34446007, 2021). "Quantitative real-time PCR (qRT-PCR) analysis was carried out to detect the RNA expression of IGF2BP3 in A375 cell line, melanoma tissues, and normal tissues." (PMID 34446007, 2021). "The results demonstrated that IGF2BP3 mRNA level was upregulated in melanoma tissues as well, while RBM15B and METTL16 was insignificant, though high expression of RBM15B and METTL16 were associated with poor OS in TCGA database." (PMID 34446007, 2021). "The correlations of IGF2BP3 and immune cells is explored in melanoma using the Tumor Immune Estimation Resource (TIMER; cistrome.shinyapps.io/timer) database." (PMID 34446007, 2021). "The results of TMA also confirmed that IGF2BP3 was significantly up-regulated in melanoma, and also confirmed that SPRR1B was significantly down-regulated in metastatic cancer before tumor invasion and metastasis." (PMID 34737950, 2021). "IGF2BP3 has indeed been reported to participate in tumorigenicity in numerous kinds of cancers included melanoma." (PMID 34446007, 2021). "Particularly, IGF2BP3 CNV has evidently correlated with immune infiltration in melanoma, including B cells, CD4 + T cells, CD8 + T cells, macrophages, neutrophils and dendritic cells." (PMID 34446007, 2021). "IGF2BP3 was found to be upregulated in a variety of malignant tumors including lung, esophageal cancers and melanomas, and was capable of promoting tumor growth, drug-resistance and metastasis." (PMID 30710069, 2019). "IGF2BP3 has been found to be significantly highly expressed in metastatic melanomas, compared with thin melanomas." (PMID 23069990, 2013). "In melanoma, IGF2BP3 promoted metastasis in an m6A‐dependent manner." (PMID 38073586, 2023). "Epigenetic silencing of CDR1as drives IGF2BP3-mediated melanoma invasion and metastasis." (PMID 38098508, 2023).
melanoma (continued). "Since the IGF2BP3 paralogue IGF2BP1 was reported to be loaded in EVs derived from metastatic pancreatic and melanoma cells, we examined whether IGF2BP3 was released by EWS cells into the supernatants as a free soluble molecule or loaded into EVs." (PMID 37353558, 2023). "To decipher the prognostic value of IGF2BP3 for melanoma progression, we analyzed the IGF2BP3 expression in primary melanomas, measured by RT-qPCR and immunohistochemistry, and studied its potential correlation with widely accepted clinicopathologic prognostic factors." (PMID 35565448, 2022). "IGF2BP3 immunostaining was higher in metastatic melanomas than in thin primary melanomas." (PMID 35565448, 2022). "Our study retrospectively examines IGF2BP3 mRNA and protein expression in primary melanomas, their correlation with clinicopathologic factors, clinical outcome, and selected miRNAs expression, and their efficiency in predicting melanoma progression and survival." (PMID 35565448, 2022). "To date, most IGF2BP3 studies on melanoma have analyzed it by immunohistochemistry (IHC)." (PMID 35565448, 2022). "Moreover, high levels of IGF2BP3 played an important role in cell proliferation, as well as in the processes of invasion, migration, and metastasis in melanoma." (PMID 35565448, 2022). "Interestingly, higher IGF2BP3 mRNA expression was detected in primary melanomas that further metastasized to distant sites and was an independent prognostic factor for the risk of unfavorable DMFS and MSS." (PMID 35565448, 2022). "RBM15, VIRMA, IGF2BP3, and YTHDF3 were frequently overamplified in melanoma patients, while VIRMA displayed missense mutations with unknown significance." (PMID 34446007, 2021). "Recent research showed that IGF2BP3 exerts a vital part in melanoma invasion and metastasis." (PMID 33637103, 2021). "We have verified the oncogenic functions of IGF2BP3 in melanoma via cell functional experiments." (PMID 34446007, 2021). "Therefore, we thought IGF2BP3 was a gene worthy for further analysis of its strong correlation with melanoma." (PMID 34446007, 2021). "Although both IGF2BP3 mRNA and protein significantly correlated, this correlation was moderate (r = 0.51, p < 0.001 and r = 0.46, p < 0.001 for H-score 1 and 2, respectively), and the IGF2BP3 protein hardly correlated with the clinicopathologic melanoma features." (PMID 35565448, 2022). "Our findings support the use of IGF2BP3 mRNA levels as an independent prognostic biomarker and the implementation of its RT-qPCR analysis for routine melanoma assessment, even for the earliest stages, to improve melanoma clinical outcomes and individualized treatment." (PMID 35565448, 2022). "The result of IGF2BP3 function enrichment analysis indicated that IGF2BP3 may be related to tumor immunosuppression and tumor metastasis, so the relationship between IGF2BP3 and other m6A regulatory factors in melanoma and tumor immunity and metastasis will be further analyzed in the follow-up." (PMID 34737950, 2021). "Therefore, we further explored the expression and function of IGF2BP3 in melanoma." (PMID 34446007, 2021). "Conversely, IGF2BP3 bound and enhanced the mRNA stability of HMGA2 in the process of melanoma migration and invasion." (PMID 35676262, 2022). "Furthermore, ulcerated primary melanomas and those with vertical growth phase exhibited higher levels of IGF2BP3 mRNA and protein (H-score 1 and H-score 2) than those not ulcerated and/or with radial growth, this being significant in the case of IGF2BP3 mRNA expression." (PMID 35565448, 2022). "Thirdly, we also preliminary explored novel potential carcinogenic mechanisms of IGF2BP3 with GSEA as well as the role of RBM15B and METTL16 in melanoma, making our study more innovative and colorful." (PMID 34446007, 2021). "CiRS-7 is downregulated in melanoma and negatively correlates with melanoma progression by interacting with the RBP IGF2BP3." (PMID 32171304, 2020).
melanoma (continued). "IGF2BP3 promotes trophoblast invasion and migration via MMP9 mRNA stabilization and translation, and melanoma invasion and migration via HMGA2 mRNA stabilization and translation." (PMID 32293476, 2020). "We validated the expression pattern of circ_0079593 and the corresponding linear mRNA (IGF2BP3, Insulin Like Growth Factor 2 MRNA Binding Protein 3) in melanoma cell lines and primary melanocytic cells with and without RNase R enrichment." (PMID 39766913, 2024). "In addition to CSDE1, several RBPs have been shown to play roles in melanoma progression, including CELF, CPEB4, IGF2BP1, IGF2BP3, NOVA1 and DDX3X, among others." (PMID 38396995, 2024). "In our retrospective analysis of human melanoma patients who received immunotherapy, high levels of IGF2BP1 and IGF2BP3, but not IGF2BP2, were associated with poor clinical outcomes." (PMID 37503349, 2023). "Then, IGF2BP3 mRNA expression was proved to be an independent prognostic factor for DMFS (HR, 1.016; 95% CI: 1.005–1.028; p = 0.004) and MSS (HR, 1.024; 95% CI: 1.001–1.048; p = 0.044) together with thicker and ulcerated melanomas." (PMID 35565448, 2022). "Regarding melanoma, IGF2BP3 was found to be expressed in malignant melanomas but not in most benign nevi, even when dysplastic features were present." (PMID 35565448, 2022). "Although patients who developed distant metastasis showed a significantly higher expression level of IGF2BP3 mRNA in their primary melanomas, it was not a predictive factor for distant metastasis onset, as indicated by the logistic regression analysis." (PMID 35565448, 2022). "The IGF2BP3 protein (H-score 2) also showed this tendency but only for distant metastasis and melanoma specific survival and without reaching statistical significance." (PMID 35565448, 2022). "Third, the three prognostic panel genes (IGF2BP3, METTL16, and RBM15B) not only influenced the prognosis and clinicopathological features but were also closely correlated with tumorigenesis key signaling pathways, and hallmarks of malignant melanoma." (PMID 34446007, 2021). "Next, based on variables of three hub genes (IGF2BP3, METTL16, and RBM15B) expression derived from the all TCGA cohort, a nomogram was constructed to predict the 1-, 2-, and 3-year survival probabilities of melanoma patients." (PMID 34446007, 2021). "RT-qPCR and IHC on IGF2BP3 expression were performed in 61 cryopreserved and 63 formalin-fixed paraffin-embedded primary melanomas, respectively, and correlated to clinicopathologic factors, distant metastasis-free survival (DMFS), and melanoma -specific survival (MSS)." (PMID 35565448, 2022). "Moreover, patients with a tumor thickness lower than 4.0 mm and positive IGF2BP3 expression had a significantly worse melanoma-specific survival than those without IGF2BP3 expression." (PMID 35565448, 2022). "There are no published data about IGF2BP3 intratumoral detection by RT-qPCR in melanoma." (PMID 35565448, 2022). "In melanoma, CDR1as does not act by sponging miR-7 classically but by binding to IGF2BP3." (PMID 34716323, 2021). "Thus, this paralogue may be useful diagnostically as a marker to differentiate melanoma from benign nevi cell types characterized by little or no IGF2BP3 expression." (PMID 23069990, 2013).